EGF (epidermal growth factor)
Diseases named in the same sentence as EGF in open-access papers (continued):
Sharing a sentence is not in itself a finding about the gene and the disease.
colon carcinoma (continued). "Epidermal growth factor can induce CD55 mRNA and protein expression in HT-29 colon cancer cells through the p42/44 MAPK pathway." (PMID 40596619, 2025). "The epidermal growth factor (EGF), due to its specific and strong binding to the receptor, was successfully used as a functionalization strategy in colon cancer drug delivery, by exploiting, for example, PLGA nanoparticles or lipid-based systems." (PMID 38543324, 2024). "To confirm PKC and EGFR activation play a role in MR agonist-induced binding of βPix to β-catenin, we treated HT-29 colon cancer cells with phorbol 12-myristate, 13-acetate (PMA), a selective PKC activator and epidermal growth factor (EGF)." (PMID 37805544, 2023). "According to an in vitro study using the human colon cancer cell line HT29, proanthocyanidin-rich apple polyphenol extract prevented the phosphorylation of epidermal growth factor (EGF), which in turn suppressed the development of these cells." (PMID 37720376, 2023). "First, HT-29 colon carcinoma spheroids were treated with 108 PFU of AF488-tagged EGFHi and WT (EGF–) λ phages for up to 24 h." (PMID 36591314, 2022). "Previous studies have demonstrated that AKR1B1 inhibition by sorbinil and zopolrestat hinders EGF/FGF-induced growth, migration and invasion through GS-DHN oxidative stress mediator-induced NF-κB activation on HT29 and KM20 colon cancer cells." (PMID 36552555, 2022). "The number of colon cancer cells adherent to HMEC-1 monolayers was significantly higher for untreated and EGF-treated cells than for cells treated with xanthones." (PMID 34680113, 2021). "These CRC stem cells were isolated and amplified from human colon cancer cell line HCT116 cells by culturing cloned spheres in serum-free medium supplemented with bFGF and EGF, and analysed for the presence of stem cell markers and tumour-initiating capacity." (PMID 34795238, 2021). "While α2,6-sialylation supported adhesion and migration of colon cancer cells and metastatic spread, ST6Gal I knockdown in colon cancer cells SW480 was shown to lead to EGF-induced phosphorylation of EGFR and ERK activation." (PMID 34069424, 2021). "In the present study, we designed epidermal growth factor (EGF) modified PLGA nanoparticles containing 5Fu and oxygen-transport perfluorocarbon (PFC) to enhance therapeutic efficacy against colon cancer." (PMID 32345258, 2020). "In line with our previous finding, these data suggest that in colon cancer cells, EMT induction by two important pathways, TGF-β and EGF, transcriptionally activates PHLDB2 expression." (PMID 31346319, 2019). "Stimulation of colon cancer cells with VEGF-A and placental growth factor (PlGF) activated VEGF receptor-1 (VEGFR-1) and increased proliferation activity in an autocrine EGF/EGF receptor (EGF-R)-dependent manner." (PMID 31717527, 2019). "In colon cancer, TGIF2 was reported to interact with PKM2 to recruit HDAC3 to the E-cadherin promoter, leading to EMT upon EGF stimulation." (PMID 31871777, 2019). "In colon cancer, PGE2 and EGF, products formed by the cyclooxygenase (COX-2) pathway, have been shown to induce amphiregulin production." (PMID 29682205, 2018). "Additionally, since EGF-signaling antagonists are an important clinical tool used in treatment of several types of cancers including colon cancer, further studies are needed to determine whether tumors with A20 mutations may be potential targets for EGFR inhibition." (PMID 29718933, 2018). "Conversely, the impairment of the EGF/EGFR system afforded by the HT and cetuximab combination appears to be related to its ability to mainly provoke a growth arrest in G2/M phases in colon cancer cells." (PMID 29137335, 2017). "Previously, ERK8 has been shown to be phosphorylated and activated by serum and growth factors such as epidermal growth factor (EGF) and increased tumorigenesis of human colon cancer." (PMID 28467781, 2017).
colon carcinoma (continued). "Here, we describe the effect of two molecules, cetuximab and HT, a polyphenol from olive oil, that impair the EGF/EGFR oncogenic drive, yielding a reduced proliferation of colon cancer cells." (PMID 29137335, 2017). "This study reveals that the expression of cell surface MUC1 is a critical enhancer of EGF-induced EGFR activation in human breast and colon cancer cells." (PMID 28731466, 2017). "Hydroxytyrosol (HT), a polyphenol of olive oil, downregulates epidermal growth factor (EGFR) expression and inhibits cell proliferation in colon cancer (CC) cells, with mechanisms similar to that activated by the EGFR inhibitor, cetuximab." (PMID 29137335, 2017). "In the overall population, plasma EGF was prognostic for both OS and PFS, contradicting other observations from serum measurements of colon cancer patients." (PMID 27465221, 2016). "The colon cancer cell lines, HCT116 and SW480, were incubated with different concentrations of LL-37; epidermal growth factor (EGF) was used as a positive control." (PMID 25596747, 2015). "A recent report suggested that genistein inhibited EGF-induced proliferation, which favors dephosphorylation and nuclear retention of FOXO3 in colon cancer cells." (PMID 23686257, 2013). "In a colon cancer model, REG4 was induced by growth factors, including transforming growth factor-alpha, epidermal growth factor (EGF), basic fibroblast growth factor and hepatocyte growth factor." (PMID 23342005, 2013). "When cultured in serum free medium supplemented with 1×B27, 20 ng/ml EGF and 10 ng/ml bFGF, both HCT116 and HT29 colon cancer cells grow in large round, unattached floating spheroid colonies (termed colonospheres)." (PMID 24039918, 2013). "It is intriguing that cultured in serum-free medium supplemented with EGF and bFGF, one CD133-positve colon cancer cell is able to form a cancer sphere however CD133-negative ones are not." (PMID 23533603, 2013). "Colon carcinoma cell lines HCT116 and HT29 and pancreatic adenocarcinoma cell line Panc-1 were cultured and stimulated with neurotensin or epidermal growth factor (EGF)." (PMID 21961726, 2011). "Genistein inhibited EGF-induced proliferation, while favoring dephosphorylation and nuclear retention of FOXO3 (active state) in colon cancer cells." (PMID 21639915, 2011). "In this study, we use epidermal growth factor (EGF), a key trigger in activating the EGFR signaling pathway, to stimulate caco-2 colon carcinoma cells which were tested to overexpress EGFR." (PMID 23554613, 2010). "To better study the possible responses after stimulation with EGF and the anti EGFR molecules cetuximab and gefitinib, we began by characterizing the two human colon cancer cell lines utilized (HT-29 and Caco-2) as working models." (PMID 18691415, 2008). "In order to verify that EGFR signaling was intact in our cells, the effects of EGF treatment on the expression and activation of EGFR and ERK1/2 in HT29 human colon cancer cells was examined." (PMID 16138927, 2005). "EGF-affected CAIII mRNA expression was suppressed in the colon cancer cell lines HT29 and SW480 and in the non-cancer cell line HUVEC cells." (PMID 39590368, 2024). "Genistein reduced the proliferation of colon cancer cells by diminishing the negative impact of epidermal growth factor (EGF) on the activity of FOXO3." (PMID 39334758, 2024). "Recombinant extracellular domain of EpCAM induces EGFR phosphorylation and MAPK and Akt activation in the absence of EGF in colon cancer HCT116, Colo205 and HT-29 cells and in mesenchymal stem cells." (PMID 39594667, 2024). "A study reported that genistein inhibits tumor growth and cell proliferation by downregulating the negative effect of epidermal growth factor (EGF) on the activity of forkhead box O3 (FOXO3) in a colon cancer model." (PMID 35883653, 2022).
colon carcinoma (continued). "In this work, we show that MGL S3, a genetically engineered protein comprised of MGL from Clostridium sporogenesis fused to epidermal growth factor (EGF)-like peptide, reduces, in vitro, the number of cancer cells of four different origins—neuroblastoma, lung, breast, and colon cancer." (PMID 36361596, 2022). "However, we showed that fargesin inhibited EGF-induced phosphorylation levels of mTOR and AKT in JB6 Cl41 premalignant and WiDr and HCT8 colon cancer cells." (PMID 33669811, 2021). "Targeted EGF-PLGA@5Fu/PFC NPs exhibited higher cellular uptake than non-targeted NPs into colon cancer cells." (PMID 32345258, 2020). "We developed epidermal growth factor (EGF) functionalized PLGA nanoparticles (NPs) co-loaded with 5-fluorouracil (5Fu) and perfluorocarbon (PFC) (EGF-PLGA@5Fu/PFC) for targeted treatment of colon cancer." (PMID 32345258, 2020). "Although trametinib is an effective medicine to suppress the growth of colon cancer cells, the expression of the ERRα was not completely suppressed by trametinib in the presence of the EGF." (PMID 30185207, 2018). "Although trametinib is an effective drug that suppresses the growth of colon cancer cells, it did not achieve adequate cytotoxicity and inhibit the over-expression of ERRα induced by EGF." (PMID 30185207, 2018). "Others have shown that decreased ST6Gal1 may increase EGF-induced EGFR phosphorylation and ERK1/2 activation in colon cancer cells." (PMID 30187356, 2018). "Moreover, they link CDX2 to EGF-mediated cancer cell proliferation, migration and invasion, and provide a basis to further dissect the role of CDX2 in colon cancer progression." (PMID 19781065, 2009). "EGF treatment rapidly induced phosphorylation of both EGFR and ERK1/2 in HT29 colon cancer cells." (PMID 16138927, 2005). "Therefore, EGF-effective regulation of CAIII has been investigated in both colon cancer models and non-carcinoma cell models." (PMID 39590368, 2024). "In conclusion, this study provides fundamental information on the regulatory molecular mechanisms of EGF-induced HO-1 expression through the c-Src, NADPH oxidase, ROS, PI3K, and Akt signaling pathway in increasing NF-κB activation and HO-1 protein expression in human HT-29 colon cancer cells." (PMID 25122478, 2014). "In addition, in colon cancer, activation of the Rho/Rho-kinase pathway inhibits the capacity of EGF to promote Akt activation, but not ERK1/2." (PMID 23919615, 2013). "We hypothesize that anti-proliferative properties of genistein in colon cancer cells are mediated by inhibition of the negative effect of EGF on FOXO3 activity, thus promoting cell cycle arrest." (PMID 21639915, 2011). "We investigated the potential role of the anti-tumorigenic interferon α (IFN-α) and the mitogenic epidermal growth factor (EGF) on CysLT2R regulation using non-transformed intestinal epithelial cell lines and colon cancer cells to elucidate the effects on the CysLT2R expression and regulation." (PMID 22194989, 2011).
colon carcinoma (continued). "Our results let conclude that DC‐2 treatment in HeLa cells and SW480 colon carcinoma cells might have impacted the localization and functionality of different palmitoylation substrates like HRas and ERK1/2, and likely sensitized EGFR to epidermal growth factor (EGF) stimulation." (PMID 40205982, 2025). "Moreover, the high basal level of phosphorylated FOXO3 (inactive) in sub-confluent HT-29 cells was significantly diminished by genistein, further supporting that genistein promotes FOXO3 activity in proliferative colon cancer cells regardless of EGF stimulation." (PMID 21639915, 2011). "Since HT-29 human colon cancer cells are not sensitive to EGF stimulation due to the lack of a canonical peroxisome proliferator-activated receptor-gamma response element (PPRE), we speculated that EGF may regulate caveolin-1 expression through peroxisome proliferator-activated receptor-gamma." (PMID 19816600, 2009). "The cytotoxic effect of this cytokine was analyzed in colon cancer models, HT-29 and SW480, and a non-cancer model, HUVEC cells, to which 20 ng EGF was applied." (PMID 39590368, 2024). "Our results show that established colon cancer cell lines can be cultured in 3-D matrigel, and like their original source, human CRC, do not require the presence of EGF, R-Spondin1, Wnt3a, or Noggin for proliferation and long term expansion." (PMID 23638973, 2013). "Since the activation of Wnt/β-catenin and EGF/Ras-MAPK signaling is not always clear in lung and tongue SCCs compared with colon cancers and lung adenocarcinomas, ARL4C might function as an oncogene in a certain types of cancers in which growth factor signaling is not constitutively activated." (PMID 27835592, 2016).
gastric cancer (126 papers, 1995 to 2025). A primary or metastatic malignant neoplasm involving the stomach. "In an EGF gene promoter polymorphism study, rs11568835 was associated with a decreased risk of gastric cancer as haplotypes made with two other promoter SNPs of EGF gene (rs4444903 and rs3756261) in the Chinese population." (PMID 31906817, 2020). "Based on the search strategy, seven studies evaluating the EGF +61A/G polymorphism and gastric cancer susceptibility were identified." (PMID 25729328, 2014). "This meta-analysis suggested that the EGF +61A/G polymorphism contributes to increased gastric cancer risk, especially in Asian populations." (PMID 25729328, 2014). "Some studies suggested that EGF +61A/G polymorphism was associated with an increased susceptibility to gastric cancer." (PMID 25729328, 2014). "Despite the limitations, this meta-analysis strongly suggests that the EGF +61A/G polymorphism contributes to increased gastric cancer susceptibility, especially in Asian populations." (PMID 25729328, 2014). "This is, to our knowledge, the first comprehensive meta-analysis of genetic studies on the association between EGF +61A/G polymorphism and gastric cancer." (PMID 25729328, 2014). "To date, several epidemiological studies have investigated the association between EGF +61A/G polymorphism and gastric cancer risk, but the results remain inconclusive." (PMID 25729328, 2014). "In this study, there was only one study for Caucasians concerning the EGF +61A/G polymorphism on gastric cancer risk." (PMID 25729328, 2014). "Statistical significant heterogeneity among studies was observed in the association analysis between the EGF +61A/G polymorphism and gastric cancer risk in the overall populations (GG vs. AA: PQ = 0.074; GG vs. AG + AA: PQ = 0.048)." (PMID 25729328, 2014). "Eligible studies on the association between EGF +61A/G polymorphism and gastric cancer risk were identified by search of electronic databases including PubMed, EMBASE, Cochrane Library, and Chinese Biomedical Literature database (CBM)." (PMID 25729328, 2014). "To evaluate the effects of these EGF functional SNPs in gastric cancer susceptibility, we conducted genotyping analyses for these SNPs in 387 gastric cancer cases and 392 cancer-free controls in a Chinese population." (PMID 23420566, 2013). "In this case-control study, we investigated the seven functional polymorphisms of the EGF gene with the association of gastric cancer." (PMID 23420566, 2013). "The aim of this study was to explore the associations of functional EGF gene polymorphisms and risk of gastric cancer in a Chinese population." (PMID 23420566, 2013). "In addition, studies linking this locus with gastric cancer risk have shown that the T allele increases gastric cancer susceptibility by regulating EGF‐mediated inflammatory responses and mucosal repair disorders." (PMID 40696566, 2025). "Our meta-analysis based on six case–control studies suggested that the EGF +61A/G polymorphism contributes to increased gastric cancer susceptibility, which was consistent with the hypothesis above." (PMID 25729328, 2014). "Variation of the EGF +61A/G (rs4444903) can lead to an alteration in EGF production and/or activity, which may result in individual susceptibility to gastric cancer." (PMID 25729328, 2014). "It is, therefore, biologically reasonable to hypothesize a potential relationship between the EGF +61A/G polymorphism and gastric cancer." (PMID 25729328, 2014). "In light of the important biological function of the EGF +61A/G polymorphism, emerging epidemiological studies have been performed to investigate the association of EGF +61A/G polymorphism with gastric cancer risk, but the results remain inconsistent and underpowered." (PMID 25729328, 2014).